DCBLD2 (discoidin, CUB and LCCL domain containing 2)
Diseases named in the same sentence as DCBLD2 in open-access papers (continued):
Sharing a sentence is not in itself a finding about the gene and the disease.
developmental delay (1 paper, 2021). "In this report, a novel variant in the DCBLD2 gene associated with RCM, developmental delay, spasticity, and dysmorphic features was reported for the first time in a Saudi patient." (PMID 34145321, 2021). "In this study, we report the identification and functional characterization of a novel homozygous nonsense mutation in exon 1/16 of the DCBLD2 gene (c.80G > A, p.W27*) in a Saudi patient presenting with a multisystem disorder including RCM, developmental delay, spasticity and dysmorphic features." (PMID 34145321, 2021). "In summary, our analysis identifies a homozygous nonsense variant in DCBLD2 that might be associated with RCM, developmental delay and dysmorphic features." (PMID 34145321, 2021). "Taken together, these results suggest that Ca2+ and ROS dysregulation may be associated with the pathogenesis of developmental delay, RCM, and spasticity characterized in patients with the identified DCBLD2 variant." (PMID 34145321, 2021). "Therefore, the W27* variant in the DCBLD2 gene was considered the most likely candidate for a disease-causing variant with a potential relationship with the patient’s phenotype, including RCM, developmental delay, spasticity, and dysmorphic features." (PMID 34145321, 2021).
essential hypertension (1 paper, 2023). Hypertension that presents without an identifiable cause. "By constructing the ceRNA regulatory network, we found that lncRNA PVT1-miR-139-5p-DCBLD2 has a potential ceRNA regulatory mechanism involved in the development of essential hypertension in Xinjiang Kazakh people." (PMID 37396592, 2023). "Our study reveals a new ceRNA regulatory network, lncRNA PVT1-miR-139-5p-DCBLD2, providing new insights into the mechanism of essential hypertension in Xinjiang Kazakh." (PMID 37396592, 2023). "The potential role of lncRNA PVT1-miR-139-5p-DCBLD2 in the process of essential hypertension in Xinjiang Kazakh needs to be further verified in future studies." (PMID 37396592, 2023). "lncRNA PVT1-miR-139-5p-DCBLD2 was indicated to comprise a potential ceRNA regulatory mechanism involved in the development of essential hypertension in the Xinjiang Kazakh population." (PMID 37396592, 2023). "Furthermore, we constructed a ceRNA regulatory network related to differentially expressed lncRNAs, among which lncRNA PVT1-miR-139-5p-DCBLD2 may have a potential ceRNA regulatory mechanism in the occurrence of essential hypertension in Xinjiang Kazakh people." (PMID 37396592, 2023). "Therefore, we hypothesized that lncRNA PVT1-miR-139-5p-DCBLD2 has a potential ceRNA regulatory mechanism in the occurrence of essential hypertension in Xinjiang Kazakh and that all RNAs in this ceRNA network may be biomarkers for the diagnosis of essential hypertension in this population." (PMID 37396592, 2023).
glioma (1 paper, 2021). A benign or malignant brain and spinal cord tumor that arises from glial cells (astrocytes, oligodendrocytes, ependymal cells). "Phosphorylated DCBLD2 can recruit TRAF6 and stimulate the AKT pathway, promoting the migration and invasion abilities of glioma cells." (PMID 33579282, 2021).
Insulin resistance (1 paper, 2025). Increased resistance towards insulin, that is, diminished effectiveness of insulin in reducing blood glucose levels. "Specifically, they showed elevated IL1RN (a marker of systemic inflammation), ANGPTL4 (a key regulator of lipid metabolism), DCBLD2 (associated with insulin resistance), and LEP (a hormone for long-term energy balance)." (PMID 40528258, 2025).
invasive breast carcinoma (1 paper, 2010). A carcinoma that infiltrates the breast parenchyma. "DCBLD2/ESDN was also shown to be part of an invasive breast cancer gene signature." (PMID 20525283, 2010).
myxofibrosarcoma (1 paper, 2021). A malignant fibroblastic neoplasm arising from the soft tissue. "DCBLD2 expression could be a useful diagnostic biomarker to evaluate invasive properties of myxofibrosarcoma, but its diagnostic value in PDAC remained unclear." (PMID 33834039, 2021).
oral squamous cell carcinoma (1 paper, 2023). "The expression of AXL, SCG5, VOPP1, DCBLD2 and DRAM in oral squamous cell carcinoma were significantly higher in the TCGA database than in normal tissues." (PMID 37925175, 2023).
pancreatic ductal adenocarcinoma (1 paper, 2021). An infiltrating adenocarcinoma that arises from the epithelial cells of the pancreas. "However, the correlation of DCBLD2 expression value with the diagnosis and prognosis of pancreatic ductal adenocarcinoma (PDAC) has not yet been elucidated." (PMID 33834039, 2021).
tongue squamous cell carcinoma (1 paper, 2023). A squamous cell carcinoma that arises from the tongue. "Eight genes were shown to be related to the prognosis in patients with tongue squamous cell carcinoma (AXL, SCG5, VOPP1, DCBLD2, DRAM, DUSP1, AQP5, BLNK)." (PMID 37925175, 2023).
tumor (28 papers, 2008 to 2025). "A recent analysis revealed that upregulation of DCBLD2 is associated with tumor immunosuppression across multiple cancer types." (PMID 37292664, 2023). "The association between DCBLD2 and tumor stage, prognosis, pathway activity, immune escape, and drug sensitivity was confirmed." (PMID 36034778, 2022). "Following the confirmation of the broad-spectrum effect of DCBLD2 on tumor prognosis, we sought to investigate the mechanism underlying this effect." (PMID 36034778, 2022). "Studies have shown that DCBLD2 overexpression promotes tumor invasion and migration, causing poor prognosis." (PMID 34095137, 2021). "Clinically, DCBLD2 up-regulation has been associated with tumor progression and poor prognosis in CRC patients." (PMID 33114016, 2020). "DCBLD2 might be a potential immunological, oncogenic, as well as prognostic hallmark in terms of pan‐cancer, which could contribute to the tumor prognosis improvement and the targeted therapy development." (PMID 38602284, 2024). "To deeper explore the molecular mechanism underlying the effects of DCBLD2 expression level on tumor development, immune regulation and drug sensitivity, we found the potential DCBLD2 binding proteins and genes related to DCBLD2 expression and carried out enrichment analysis." (PMID 36034778, 2022). "GDSC database analysis showed that DCBLD2 overexpression caused tumor cell resistance to 5-FU." (PMID 34095137, 2021). "DCBLD2 might facilitate tumor progression and bore strong diagnostic, prognostic and therapeutic value in PDAC." (PMID 33834039, 2021). "Moreover, gene set enrichment analysis (GSEA) showed that genes associated with EMT, which is closely related to tumor metastasis, were significantly enriched in the DCBLD2-high samples among the LUAD specimens from the TCGA database." (PMID 33808696, 2021). "Over expression of DCBLD223 may act as an oncogene interacting with the EGFR and PI3K/Akt signaling pathways; gain of function of DCBLD2 mutation (Indel) could participate with cellular proliferative pathways to promote tumor progression." (PMID 26619400, 2015). "Furthermore, DCBLD2 mRNA levels were linked to tumor stage in CHOL, HNSC, KIRP, LUSC, and THCA." (PMID 36034778, 2022). "Examples include MANF, DCBLD2, and PLK2, which have been linked to tumor-suppressive functions in various cancers." (PMID 41154614, 2025). "Second, we lacked further studies to investigate the mechanisms by which DCBLD2 affects tumor cell migration and invasion." (PMID 39790460, 2025). "According to these results, we further analyzed immune infiltration in different TCGA tumor types grouped according to DCBLD2 expression." (PMID 38714870, 2024). "To determine the immunological components of DCBLD2 in the tumor microenvironment across various cancers, we conducted a comprehensive analysis using TIMER 2.0." (PMID 38714870, 2024). "Our research revealed that iAge-CRGs are expressed in a wide range of tumor types, and these genes, especially DCBLD2, are notably upregulated in most tumors." (PMID 38714870, 2024). "In this study, the expression of DCBLD2 was found to be positively correlated with the expression of CAFs, which facilitate tumor growth, angiogenesis, invasion, metastasis, and extracellular matrix remodeling." (PMID 38714870, 2024). "In the in vitro experiments, RGDfC-Se@siDCBLD2 remarkably inhibited the migration of HCT-116 cells and induced tumor cell apoptosis through the down-regulation of DCBLD2 expression." (PMID 37477789, 2023). "Next, we employed the GSCA database to elucidate the correlation between DCBLD2 expression with tumor-related pathway activity." (PMID 36034778, 2022). "For the first time, this study: 1) Examined the effect of DCBLD2 on tumor pathological stage and prognosis from a pan-cancer perspective and discovered that DCBLD2 has a broad-spectrum activating effect on EMT signalling in all tumors." (PMID 36034778, 2022).
tumor (continued). "Results from differential expression of DCBLD2 across different tumor stages showed that this gene was significantly upregulated in highly malignant pathological tumors including CHOL, HNSC, KIRP, LUSC, and THCA (p < 0.05)." (PMID 36034778, 2022). "We analyzed the influence of DCBLD2 expression on overall survival (OS) of patients with different tumor types via TCGA dataset." (PMID 36034778, 2022). "We identified 12 markers for LUAD3, including DCBLD2, MCAM and VIM, which are considered EMT markers that are usually associated with tumor dedifferentiation and poor prognosis in NSCLC44–46." (PMID 35383171, 2022). "The results showed that the mRNA expression of DCBLD2 in LUAD tumor tissues was higher than that in normal tissues (p = 0.0003)." (PMID 33808696, 2021). "To detect DCBLD2 protein expression in LUAD, we evaluated 102 paired LUAD tissues and normal tissues from the CPTAC database and found that DCBLD2 expression was higher in tumor tissues than in normal tissues (p = 0.0049)." (PMID 33808696, 2021). "We also mixed DCBLD2-overexpessing A549 cells and empty vector-transfected cells at a ratio of 1:1 before injecting them subcutaneously into mice to generate the tumor xenografts composed of cells with heterogeneous expression of DCBLD2." (PMID 33808696, 2021). "To further investigate the anti-metastatic effects of DCBLD2-targeted therapy in vivo, we used a jetPEI nanocarrier as the vehicle for DCBLD2-specific siRNAs to inhibit DCBLD2 expression in tumor-bearing mice." (PMID 33808696, 2021). "The discoidin, CUB and LCCL domain-containing protein 2 (DCBLD2) is a type-I transmembrane protein which has been discovered to have considerable tumor-specific functions." (PMID 33834039, 2021). "DCBLD2 significantly reduced E-cadherin expression and increased Vimentin expression in tumor tissues in situ, as shown by IHC staining." (PMID 33808696, 2021). "The results showed that DCBLD2 expression was significantly higher in tumor tissues than that in adjacent tissues (Z = −3.524, p < 0.001)." (PMID 33808696, 2021). "Mouse tumor tissue immunohistochemical analysis showed that DCBLD2 down-regulation significantly suppresses protein level." (PMID 34095137, 2021). "GDSC database was used to analyze the effect of DCBLD2 expression difference on 5-FU drug sensitivity on tumor cells." (PMID 34095137, 2021). "Of these, ADM, DCBLD2, EREG, ITGA5, MIF, MMP14, and TREM1 were associated with poor prognosis and significantly increased in tumor, while BTG2 was related to favorable prognosis and decreased in tumor." (PMID 35002712, 2021). "Clinically, in patients with LUAD, high levels of DCBLD2 correlated with advanced tumor staging, nodal involvement, and poor survival and were shown to be a prognostic predictor." (PMID 33808696, 2021). "Our data revealed that DCBLD2 mRNA expression was remarkably increased in tumor tissues compared with normal lung tissues." (PMID 33808696, 2021). "Remarkably, low membrane-associated expression of DCBLD2 and overexpression of NT5E in tumor cells was strongly associated with shorter survival (p=5.97·10-7and p=1.01·10-5 respectively)." (PMID 24133572, 2013). "The in vivo results suggested that NT5E and DCBLD2 are involved in tumor invasion and metastasis likely through a tumor-induced immunosuppressive mechanism." (PMID 24133572, 2013). "AKAP12 and DCBLD2 were frequently detected at lower levels in tumor (T) than normal matched tissues (N)." (PMID 24133572, 2013). "A better comprehension of the TFAP2A-driven regulation of the DCBLD2/ESDN gene should provide novel and useful insights on mechanisms of tumor progression and metastasis formation." (PMID 20525283, 2010). "In addition, we revealed the specific role of DCBLD2 in the tumor microenvironment and its critical impact on BLCA progression by regulating cell migration and invasion mechanisms, highlighting its potential as a therapeutic target for BLCA." (PMID 39790460, 2025).
tumor (continued). "For example, DCBLD2 can promote tumor metastasis by stimulating EMT." (PMID 39790460, 2025). "The DCBLD2 gene is involved in angiogenesis, tumorigenesis, tumor progression, and could be exploited as a therapeutic target for the regulation of angiogenesis." (PMID 37925175, 2023). "This led us to the speculation that DCBLD2 may escape immune killing via T cell exclusion, resulting in tumor malignancy and metastasis." (PMID 36034778, 2022). "Our results showed that DCBLD2 is a potential oncogenic, immunological as well as a prognostic biomarker in terms of pan-cancer, and is expected to contribute to the improvement of tumor prognosis and the development of targeted therapy." (PMID 36034778, 2022). "In addition, DCBLD2, CASP7, TSC22D1, ANXA7, PRKAR2A, ZMYND11, and PAK2 have been reported to be tightly linked to tumor malignancy in previous studies." (PMID 35513372, 2022). "Collectively, these results suggested that DCBLD2 expression is associated with activation of the EMT signal in pan-cancer and thus may promote tumor metastasis." (PMID 36034778, 2022). "The present investigation found that DCBLD2 expression was inversely related to the IPS score, implying that high DCBLD2 expression may cause tumor immunosuppression." (PMID 36034778, 2022). "Following that, we validated the positive correlation between DCBLD2 expression with infiltration of CAFs and MDSCs using the TIMER2.0 database, then employed the ESTIMATE package in R to quantify and visualize the impact of DCBLD2 on immune cell infiltration in specific tumor types." (PMID 36034778, 2022). "The analysis of the relationship between DCBLD2 expression and sensitivity to chemotherapy of all solid tumor cells showed a positive correlation of DCBLD2 expression level in tumor cell lines with the IC50 values of many chemotherapeutic drugs, targeted drugs, and small molecular probes." (PMID 36034778, 2022). "First, we investigated the oncogenic action of DCBLD2 in total tumor types from TCGA data." (PMID 36034778, 2022). "Based on the findings, we hypothesize that high DCBLD2 expression may reduce the efficacy of chemotherapy or targeted therapy in tumor patients and that the gene may be a potential biomarker for drug efficacy evaluation or new drug development." (PMID 36034778, 2022). "DCBLD2 overexpression promotes tumor occurrence, development, and metastasis." (PMID 34095137, 2021). "By contrast, DCBLD2 knockdown markedly reduced tumor metastasis." (PMID 33808696, 2021). "Therefore, this study provided the reference for clarifying the potential biological role of DCBLD2 in tumor immunology and PDAC progression." (PMID 33834039, 2021). "Moreover, DCBLD2-targeted siRNA encapsulated by jetPEI nanocarriers significantly inhibited DCBLD2 expression and tumor metastasis in vivo during cisplatin treatment." (PMID 33808696, 2021). "Importantly, DCBLD2-specific siRNAs encapsulated by nanoparticles strikingly inhibited cisplatin-induced metastasis in tumor-bearing mice." (PMID 33808696, 2021). "In few tumor sections, DCBLD2 immunopositivity was also localized to the cytosolic compartment." (PMID 24133572, 2013). "Thus, we need to further clarify whether silencing DCBLD2 by siRNA delivery platform exhibit good antitumor efficacy in tumor-bearing mice model." (PMID 37477789, 2023). "Results revealed that DCBLD2 expression was not only inversely associated with all indexes across all tumors, except EC, but also with the final IPS score, suggesting that its upregulation may cause tumor immunosuppression." (PMID 36034778, 2022). "However, DCBLD2 sensitivity to chemotherapy drugs and its mechanism on tumor development are unknown." (PMID 34095137, 2021). "However, DCBLD2 sensitivity to chemotherapy drugs and its mechanism in tumor development and metastasis are unknown." (PMID 34095137, 2021).